NFKB1 (nuclear factor kappa B subunit 1)
Diseases named in the same sentence as NFKB1 in open-access papers (continued):
Sharing a sentence is not in itself a finding about the gene and the disease.
cancer (10,094 papers, 1999 to 2026). A tumor composed of atypical neoplastic, often pleomorphic cells that invade other tissues. "NFKB1 encoded a key component of the NF-κB transcription factor complex, which was critical in the occurrence and development of various diseases including cancer." (PMID 40666524, 2025). "CHUK and NFKB1 are engaged in a complex crosstalk linked to cancer progression and drug resistance due to their ability to activate inflammatory responses and promote cell survival." (PMID 40650045, 2025). "The epigenetic activity of transcription factor motifs linked to cancer immunogenicity, e.g., Irf1/2/8/9, Stat1, and Nfkb1, were increased in KO cells, which coincided with findings in a PRRX1-overexpressing cell line model." (PMID 39255035, 2024). "MED12 is involved in regulating essential steps of transcription, and its deregulation was linked to human cancers, while NFKB1 plays a role in macrophage polarization and innate immune memory responses." (PMID 39639867, 2024). "The NFkB pathway, a regulator of immune and inflammatory responses, also implicated in cancer cell proliferation, survival, angiogenesis and plasticity, was downregulated at the level of NFkB (NFKB1) itself and IKK kinase (CHUK)." (PMID 39495207, 2024). "A meta-analysis reveals that the -94ins/del polymorphism within the NFKB1 promoter is linked to cancer susceptibility, with potential ethnic-specific associations." (PMID 39432502, 2024). "In the CircRNA enrichment analysis, among the cancer-associated pathways, only Nfkb1, was found to be involved in all types of cancer and cancer-associated pathways." (PMID 37047531, 2023). "NFκB1 is a subunit of NF-κB, whose aberrant activation is considered associated with cancer pathogenesis." (PMID 35896012, 2022). "Growing evidence has pointed to the involvement of NFKB1 −94ins/delATTG polymorphism analysed here (rs28362491) in cancer susceptibility." (PMID 34672421, 2021). "CVID resulting from NFKB1 loss of function is characterised by lymphadenopathy, splenomegaly, and autoimmunity, as well as an increased incidence of cancers including solid tumours and hematologic malignancies." (PMID 34721373, 2021). "Suppression of STBD1—either via knockdown or expression of the mutant—also promotes the expression of multiple cancer hallmark genes, including c-Myc, NFKB1, and AKT1, although the exact underlying mechanisms remain to be determined." (PMID 34059679, 2021). "Our own studies and those of others further associate certain functional polymorphisms particularly in NFKB1 to increased susceptibility for various cancers." (PMID 34572737, 2021). "The best characterised variant is rs28362491, a four-nucleotide biallelic indel in the NFKB1 promoter that was linked to differences in gene expression and seems to be associated with the risk of developing several types of cancer." (PMID 31815120, 2019). "Survival data curated from The Cancer Genome Atlas (TCGA) revealed that the expression of cEBPβ, cJun, cFos, and NFkB1 were associated with poor patients’ survival." (PMID 30765860, 2019). "The mean mutant allele frequency for G430E in NFKB1 in cancer cells before radiotherapy was only 9.8%, while the mean mutant allele frequency in cancer cells after radiotherapy was 31.9% (P = 0.048)." (PMID 29484114, 2018). "Conversely, we found that the del allele of the NFKB1 -94ins/delATTG polymorphism conferred a significantly decreased risk of cancer in the pooled analysis." (PMID 28039461, 2017). "In this meta-analysis, we found that the NFKB1 -94ins/delATTG promoter polymorphism was significantly associated with decreased overall cancer risk under the five genetic models." (PMID 28039461, 2017).
cancer (continued). "Numerous case-control studies have assessed the association between the NFKB1 -94ins/delATTG promoter polymorphism and cancer risk, with discrepant results." (PMID 28039461, 2017). "As most of the studies were performed on the Chinese population, we determined the association of NFKB1 -94ins/delATTG polymorphism with cancer risk on Chinese subjects." (PMID 28039461, 2017). "According to TCGA pan-cancer data, mutations in NFKB1 are scattered along the protein with moderate enrichment within the ankyrin repeat domain, but the mutations are quite infrequent." (PMID 28636652, 2017). "In conclusion, despite these limitations, and in agreement with several previous studies, this meta-analysis draws the robust conclusion that NFKB1 -94ins/delATTG polymorphism is associated with decreased cancer risk, especially in the Asian population." (PMID 28039461, 2017). "Second, we assessed the association between the NFKB1 -94ins/delATTG polymorphism and cancer risk from a genetic perspective only, by using unadjusted ORs." (PMID 28039461, 2017). "We conclude that the NFKB1 −94ins/del ATTG promoter polymorphism is associated with cancer risk not only in Asian populations, but also in Caucasian populations." (PMID 27463002, 2016). "The human NFKB1 gene, located on chromosome 4q24, encodes a 50 kDa DNA-binding protein that can act as a master regulator of inflammation and cancer development." (PMID 27463002, 2016). "In this meta-analysis, we investigated the -94 ins/del ATTG on NFKB1 gene locus with 42 separate case-control studies (18,222 cases and 24,778 controls) focusing on the relationship of this variant to cancer risk." (PMID 27443693, 2016). "The subgroup analysis for ethnicity found that the NFKB1 −94ins/del ATTG promoter polymorphism was significantly associated with an increased susceptibility to cancer in Asians and with a decreased susceptibility in Caucasians." (PMID 27463002, 2016). "Many researchers have been studying the aetiology of oncogenesis, and have identified the relationship between genetic polymorphism and cancer risk, especially for the NFKB1 −94ins/del ATTG promoter polymorphism." (PMID 27463002, 2016). "Previous studies have identified several single nucleotide polymorphisms (SNPs) in NFκB1/NFκB2 and IκBα to be associated with a great variety of diseases including inflammatory disorder and cancer." (PMID 26161396, 2015). "Nuclear factor-κB is associated with the pathogenesis of numerous malignancies, and the functional polymorphism −94ins/del ATTG (rs28362491) in the human NFKB1 gene is associated with cancer risk." (PMID 24895544, 2014). "A four base pair deletion polymorphism in NFKB1 i.e., -94ATTG del is extensively explored in various cancers." (PMID 24324738, 2013). "A recent meta-analysis study also indicated an association between the NFKB1 -94 Ins promoter polymorphism and the incidence of cancer in Caucasian and Asian populations." (PMID 23457512, 2013). "A functional -94 insertion/deletion polymorphism (rs28362491) in the promoter of the NFKB1 gene was reported to influence NFKB1 expression and confer susceptibility to different types of cancer." (PMID 23977085, 2013). "Our data from this relatively large sample size study further support the notion that the NFκB1 and NFκBIA polymorphisms are potentially implicated in cancer risk." (PMID 21738780, 2011). "The significance of NFKB1 as a suppressor of the NF-κB response is evident in mouse models, where Nfb1(-/-) mice exhibit increased inflammation and susceptibility to certain forms of DNA damage, leading to cancer and an accelerated aging phenotype." (PMID 37954148, 2023). "The significance of NFKB1 function could be observed in models of mouse: Nfkb1−/− mouse showed intensified inflammatory response and susceptibility to DNA injury in some forms and finally suffered cancer and quick aging phenotype." (PMID 35502302, 2022).
cancer (continued). "In addition, studies have shown that the loss of NFKB1 can lead to inflammation and the progression of cancer by increasing the expression of TNF." (PMID 35127830, 2022). "However, role of NFKB1 −94ins/delATTG polymorphism in specific cancer is contradictory, namely a decreased cancer susceptibility or a null association." (PMID 34672421, 2021). "Nfkb1 function can be seen in mouse models, where Nfkb1 –/–mice display increased inflammation and susceptibility to certain forms of DNA damage, leading to cancer." (PMID 29484114, 2018). "Interestingly, NFKB1 was reported to be involved in inflammation-associated cancer, while HPV has been linked to chronic inflammation." (PMID 29484114, 2018). "Therefore in a pedigree with an LOF variant in NFKB1, any relatives with cancer should be suspected of sharing the same pathogenic variant." (PMID 29477724, 2018). "However, fewer studies regarding NFKB1 polymorphisms and cancer risk have been conducted in Western populations." (PMID 30205516, 2018). "Our study re-evaluated the impact of the NFKB1 -94ins/delATTG polymorphism on cancer risk." (PMID 28039461, 2017). "In addition, the γCdcPLI treatment decreased the expression of the NFKB1 gene, which encodes the NFκβ factor, also important to the survival and metastasis of cancer cells." (PMID 28765552, 2017). "Numerous studies have addressed the association of a functional insertion (I)/deletion (D) polymorphism (-94ins/delATTG, rs28362491) in the promoter region of NFKB1 gene with the risk of various types of cancer; however, their conclusions have been inconsistent." (PMID 28039461, 2017). "We found that the NFKB1 −94ins/del ATTG promoter polymorphism was significantly increased cancer risk in homozygote (II vs. DD, OR = 1.259, 95% CI = 1.068-1.485), recessive (II vs. ID+DD, OR = 1.140, 95% CI = 1.029-1.263) and allele (I vs. D, OR = 1.109, 95% CI = 1.025-1.199) genetic models." (PMID 27463002, 2016). "Due to the inconsistency of past studies and the critical role of the variant in the pathogenesis of cancer, we conducted an updated meta-analysis to investigate the association of NFKB1 -94 ins/del ATTG promoter polymorphism and cancer risk by precise results." (PMID 27443693, 2016). "Accumulating evidences have indicated that the functional -94 ins/del ATTG polymorphism in the promoter region of human nuclear factor-kappa B1 (NFKB1) gene may be associated with cancer risk." (PMID 27443693, 2016). "NFKB1 codes for a DNA-binding subunit of the NF-kappa-B (NFκB) protein complex transcription regulator, and altered expression of this gene is associated with cancer and many inflammatory diseases." (PMID 25008066, 2014). "In conclusion, the NFKB1 promoter −94ins/del ATTG polymorphism is associated with cancer risk." (PMID 24895544, 2014). "The different findings of NFKB1 -94ATTG del polymorphism may be due to its cancer specific or population specific nature of association." (PMID 24324738, 2013). "Our results reflect potential for putative crosstalk between Nrf2 and Nfkb1 modulated through the MAPK cascade that may influence inflammation-associated etiopathogenesis of cancer." (PMID 19050705, 2008). "Moreover, NFKB1 was reported to be involved in inflammation-associated cancer." (PMID 29484114, 2018). "Taken together, the elucidation of potential relationships between Nrf2 and Nfkb1 may help to better understand transcriptional regulation, as well as transcription factor networks, associated with the etiopathogenesis of inflammation and cancer." (PMID 19050705, 2008). "STAT3 interacts with NFκB1 at multiple levels; it extends NFκB1–nuclear retention, and together, they control the ability of cancer cells to resist apoptosis." (PMID 40149331, 2025). "Of particular note is a small core of microRNA-regulated proteins, which also represent important nodes in altered functions in cancer, including ErbB2, NFkB1, and Notch2." (PMID 40004024, 2025).
cancer (continued). "Among the NF-κB protein family members, including RelA, RelB, c-Rel, p50, and p52, p50 (NFKB1) has been identified as a significant tumor-promoting factor in cancer proliferation and metastasis, correlating with poor patient survival 33,34." (PMID 41041071, 2025). "The findings demonstrated elevated NFKB1 mRNA and protein levels in the more advanced stages of oral SCC, suggesting NFKB1’s potential role in cancer progression." (PMID 40141426, 2025). "Nuclear factor kappa B subunit 1, or NFκB1, mediates immunological response and is the connecting link between inflammation and cancer." (PMID 39786519, 2025). "We have previously reported the regulatory potential for crosstalk between Nfkb1- and Nrf2-mediated gene expression in cancer and inflammation." (PMID 40636521, 2025). "Non-responder-specific gene signatures were regulated by Activator Of Transcription 3 (STAT3) and Nuclear Factor Kappa B Subunit 1 (NFKB1), known to play roles in PD-L1 regulation and T cell activation in cancer." (PMID 39514276, 2024). "The reduced intratumoral immune cell infiltration due to IL30-targeting treatment was accompanied by substantial inhibition in cancer cells expression of NFKB1, which is a key player in cancer-immune cell crosstalk and in modulating antitumor immunity." (PMID 39232121, 2024). "Collectively, our data lead us to propose that relatively low levels of active miR-214 in equine MDECs allow for the robust expression of NFKB1, and apoptosis as a protective anti-cancer response to the carcinogen DMBA." (PMID 37789172, 2023). "NFKB1 has been reported to be playing a critical role in suppressing inflammation, aging and cancer." (PMID 37605653, 2023). "The identified TFs, such as FOXC1, FOXL1, POU2F2, NFIC, NFkB1, MEF2A, GATA2, and E2F1, are mainly associated with different types of cancers and congenital disorders." (PMID 37026010, 2023). "In summary, our findings suggest that H. pylori infection accelerates early‐stage GC progression by upregulating NFKB1/RELA transcription mediated by PIEZO1 in cancer cells." (PMID 37983931, 2023). "Evidence for this stems from the detection of somatic mutations in PIK3CD, NFKB1, and STAT3 in human cancer genomes and the identification of their role in carcinogenesis." (PMID 35250968, 2022). "NFKB1 is a cancer and inflammation inhibitor that plays an inhibitory role in the occurrence and development of a number of cancers by inhibiting the NF-κB signaling pathway." (PMID 35127830, 2022). "It has been reported that NFκB1 plays multiple roles in the development and progression of different cancers." (PMID 35896012, 2022). "NF-κB transcription factors are themselves targets for mutation in many cancers, although RELA and RELB are much less frequently mutated than REL, NFKB1, and NFKB2." (PMID 34440093, 2021). "Increasing studies have found that HOXB1 participated in regulating nuclear factor kappa B subunit 1(NF-kB) pathway, cancer cell proliferation and apoptosis." (PMID 34488545, 2021). "NFKB1 also plays a dual role in apoptosis, either as inducer or as inhibitor of apoptosis; thus, NFKB1 was found to be both up- or downregulated by natural compounds in different cancers, as well as the same type of cancer." (PMID 34422220, 2021). "NFKB1 exerted an inhibitory function in the tumorigenesis and progression of different types of cancers through alleviating the abnormal activation of the NF-κB signaling." (PMID 33005178, 2020). "NFKB1 is an suppressor of inflammation and cancer, which plays an inhibitory role in the occurrence and progression by reducing the abnormal activation of NF-κB signal pathway." (PMID 32508531, 2020). "The NFKB1 gene has been described to be a key player in the ER stress pathway and cancer survival mechanisms." (PMID 32316560, 2020).
cancer (continued). "Nuclear factor-kappa B1 (NFκB1) is a pleiotropic transcription factor that contributes to tumorigenesis in many types of cancer." (PMID 32033398, 2020). "NFKB1, a suppressor of inflammation and cancer, plays an inhibitory role in the tumorigenesis and progression of a variety of cancers by reducing the abnormal activation of the NF-κB signaling pathway." (PMID 32117786, 2019). "Previous studies have demonstrated that several genetic variations of NFKB1 and NFKBIA were associated with cancer risk such as esophageal 15, gastric 16, and colorectal cancer." (PMID 29635862, 2018). "It was displayed that the expression of around 20 genes is regulated by HIF-1α, including NFκB1, which is involved in regulation of inflammation and cancer." (PMID 30123433, 2018). "This review highlights the multiple roles of NFKB1 in the development and progression of different cancers, and the considerations to make when attempting to manipulate NF-κB as a potential cancer therapy." (PMID 30205516, 2018). "Previous meta-analysis focused on the relationship between the NFKB1 −94ins/del ATTG promoter polymorphism and cancer, but the results were inconsistent." (PMID 27463002, 2016). "In the subgroup analysis of ethnicity, we found a significant association of the NFKB1 −94ins/del ATTG promoter polymorphism with increased and decreased cancer risk in Asian and Caucasian populations, respectively." (PMID 27463002, 2016). "We must know the distribution of allelic frequencies of these polymorphisms [IL-1A (rs3783553), IL4 (rs79071878), NFKB1 (rs28362491) and PAR1 (rs11267092)] for association studies on cancer, data for which is limited on Brazilian populations." (PMID 26879815, 2016). "Transcription factor NFKB1 plays an important role in the inflammatory process, and it can influence cancer development and aggressiveness, increasing tumour angiogenesis and repressing the immune response." (PMID 26879815, 2016). "We describe the allelic distributions of four IL1A (rs3783553), IL4 (rs79071878), NFKB1 (rs28362491) and PAR1 (rs11267092) gene polymorphisms, which the literature describes as polymorphisms with a risk of cancer or worse prognosis for cancer." (PMID 26879815, 2016). "We performed a meta-analysis of 37 case-control studies from 33 articles (16,271 cases and 22,781 controls) to clarify the relationship between the NFKB1 −94ins/del ATTG promoter polymorphism and cancer susceptibility." (PMID 27463002, 2016). "Since then, several other studies performed on large case and control groups have assessed the relationships between the NFKB1 −94ins/del ATTG promoter polymorphism and susceptibility to a variety of cancers." (PMID 27463002, 2016). "In conclusion, to the best of our knowledge, this is a comprehensive study to assess the relationship between NFKB1 -94 ins/del ATTG polymorphism and cancer risk." (PMID 27443693, 2016). "Although RELB, which causes cancer progression, significantly induced CCID formation the major role in this process was attributed to RELA/NFKB1 (“canonical” pathway)." (PMID 26513020, 2015). "In the case of cancer-associated small indels, the statistically most significant results were with complexes related to RELA gene—NFKB1-RELA and RELA-REL complexes both had p value 7.56E-4." (PMID 25496518, 2014). "After the reported study, numerous studies further assessed the relationship between the NFKB1 promoter −94ins/del ATTG polymorphism and cancer among Asians and Caucasians." (PMID 24895544, 2014). "An increasing number of studies have assessed the association between the NFKB1 promoter −94ins/del ATTG polymorphism and cancer risk." (PMID 24895544, 2014). "Genetic variation plays a critical role in determining cancer risk, and several studies have investigated the association between the -94 ins/del ATTG polymorphism in NFKB1 promoter and cancer risk." (PMID 23977085, 2013).